ZBTB7A (zinc finger and BTB domain containing 7A)
Description:
Transcription factor that represses the transcription of a wide range of genes involved in cell proliferation and differentiation. Directly and specifically binds to the consensus sequence 5'-[GA][CA]GACCCCCCCCC-3' and represses transcription both by regulating the organization of chromatin and through the direct recruitment of transcription factors to gene regulatory regions. Negatively regulates SMAD4 transcriptional activity in the TGF-beta signaling pathway through these two mechanisms. That is, recruits the chromatin regulator HDAC1 to the SMAD4-DNA complex and in parallel prevents the recruitment of the transcriptional activators CREBBP and EP300. Collaborates with transcription factors like RELA to modify the accessibility of gene transcription regulatory regions to secondary transcription factors (By similarity). Also directly interacts with transcription factors like SP1 to prevent their binding to DNA. Functions as an androgen receptor/AR transcriptional corepressor by recruiting NCOR1 and NCOR2 to the androgen response elements/ARE on target genes. Thereby, negatively regulates androgen receptor signaling and androgen-induced cell proliferation. Involved in the switch between fetal and adult globin expression during erythroid cells maturation. Through its interaction with the NuRD complex regulates chromatin at the fetal globin genes to repress their transcription. Specifically represses the transcription of the tumor suppressor ARF isoform from the CDKN2A gene (By similarity). Efficiently abrogates E2F1-dependent CDKN2A transactivation (By similarity). Regulates chondrogenesis through the transcriptional repression of specific genes via a mechanism that also requires histone deacetylation (By similarity). Regulates cell proliferation through the transcriptional regulation of genes involved in glycolysis. Involved in adipogenesis through the regulation of genes involved in adipocyte differentiation. Plays a key role in the differentiation of lymphoid progenitors into B and T lineages (By similarity). Promotes differentiation towards the B lineage by inhibiting the T-cell instructive Notch signaling pathway through the specific transcriptional repression of Notch downstream target genes (By similarity). Also regulates osteoclast differentiation (By similarity). May also play a role, independently of its transcriptional activity, in double-strand break repair via classical non-homologous end joining/cNHEJ (By similarity). Recruited to double-strand break sites on damage DNA, interacts with the DNA-dependent protein kinase complex and directly regulates its stability and activity in DNA repair (By similarity). May also modulate the splicing activity of KHDRBS1 toward BCL2L1 in a mechanism which is histone deacetylase-dependent and thereby negatively regulates the pro-apoptotic effect of KHDRBS1.
Synonyms: FBI-1; Pokemon; TIP21; FBI1; LRF; ZBTB7; ZNF857A; DKFZp547O146; MNDLFH
Tractability: PROTAC: UniProt records ubiquitination sites on it; ubiquitination databases record sites on it.
Target class: Transcription factor
Gene: Protein-coding gene on chromosome 19 (4,043,303 to 4,067,636, reverse strand). Ensembl gene ENSG00000178951.
Subcellular location: Nucleus
Subcellular location (Human Protein Atlas): Nucleoplasm
Gene Ontology:
Molecular function: DNA-binding transcription factor activity; DNA-binding transcription factor binding; nuclear androgen receptor binding; protein binding; RNA polymerase II cis-regulatory region sequence-specific DNA binding; sequence-specific double-stranded DNA binding; SMAD binding; transcription corepressor binding; DNA binding; DNA-binding transcription factor activity, RNA polymerase II-specific; histone acetyltransferase binding; DNA-binding transcription repressor activity, RNA polymerase II-specific; sequence-specific DNA binding
Biological process: chromatin remodeling; erythrocyte maturation; fat cell differentiation; negative regulation of androgen receptor signaling pathway; negative regulation of DNA-templated transcription; negative regulation of transcription by RNA polymerase II; negative regulation of transforming growth factor beta receptor signaling pathway; protein localization to nucleus; regulation of alternative mRNA splicing, via spliceosome; regulation of apoptotic process; regulation of glycolytic process; regulation of transcription by RNA polymerase II; regulation of transcription regulatory region DNA binding; B cell differentiation; chromatin organization; double-strand break repair via classical nonhomologous end joining; negative regulation of Notch signaling pathway; DNA-templated transcription
Cellular component: cytoplasm; nucleus; site of double-strand break; DNA-dependent protein kinase complex
Genetic constraint (gnomAD): Loss-of-function variants: 8 observed, 16.43 expected, observed/expected ratio (o/e) 0.49, 90% interval 0.28 to 0.88. The upper end of that interval is the gene's LOEUF score, 0.88, which puts it in group 3 of 6, group 1 being the genes least tolerant of losing a copy. Missense variants: 617 observed, 758.12 expected, observed/expected ratio (o/e) 0.81, 90% interval 0.76 to 0.87. Synonymous variants: 452 observed, 386.62 expected, observed/expected ratio (o/e) 1.17, 90% interval 1.08 to 1.26.
Homologues: Orthologues: chimpanzee ZBTB7A (100% identical), pig ZBTB7A (95% identical), dog ZBTB7A (93% identical), mouse Zbtb7a (87% identical), rat Zbtb7a (87% identical), guinea pig ZBTB7A (86% identical), macaque ZBTB7A (78% identical), Drosophila melanogaster klu (16% identical), Caenorhabditis elegans klu-2 (10% identical), Drosophila melanogaster CG4318 (10% identical). Paralogues in human: ZBTB5 (21% identical), ZBTB43 (18% identical), ZNF367 (13% identical), ZNF740 (7% identical).
Diseases named in the same sentence as ZBTB7A in open-access papers:
ZBTB7A is named in the same sentence as 79 diseases in open-access papers, as found by Europe PMC text mining. Sharing a sentence is not in itself a finding about the gene and the disease. The quoted sentences say what the papers report.
breast cancer (14 papers, 2008 to 2025). A primary or metastatic malignant neoplasm involving the breast. "Survival studies of patients with breast cancer, prostate cancer, pancreatic cancer, bladder cancer, hematological malignancies, and hepatocellular carcinoma have shown that high expression of ZBTB7A is associated with poor prognosis." (PMID 40471367, 2025). "While little is known about the ZBTB8 gene, the same ZBTB family protein, ZBTB7A, has been implicated in high expression in cancer tissue and the breast cancer cell lines MDA-MB-231 and MCF-7, suggesting that ZBTB8 may act as a transcriptional repressor or be involved in tumorigenesis." (PMID 33752597, 2021). "In breast cancer cells the response to KDM5 inhibitors was mediated by the level of expression of ZBTB7A transcription factor, and ZBTB7A depletion sensitized basal breast cancer cells to KDM5i." (PMID 40940894, 2025). "ZBTB7A enhances metastasis in various cancers, including colorectal cancer, breast cancer and nasopharyngeal carcinoma by facilitating epithelial-mesenchymal transition, immune modulation, and altering glycolysis." (PMID 40471367, 2025). "Our previous research confirmed that ZBTB7A was highly expressed in mammary cancer cells and tissues and that down-regulation of expression of ZBTB7A and NF-κB p65 inhibited the invasion, migration, and metastasis of MDA-MB-231 and MCF-7 cells." (PMID 35911648, 2022). "ZBTB7A was overexpressed in breast cancer tissue and promoted cell metastasis in vitro and in vivo via NF-κB induced epithelial-mesenchymal transition." (PMID 35501800, 2022). "ZBTB7A has been considered to be a proto-oncogene closely related to the occurrence and development of mammary cancer." (PMID 35911648, 2022). "Our research team has recently performed similar research in this area, and we found that capsaicin inhibits proliferation and induces apoptosis of mammary cancer cells, possibly by inhibiting the ZBTB7A-mediated NF-κB pathway." (PMID 35911648, 2022). "The expression of ZBTB7A can reflect the development and efficacy of mammary cancer to a certain extent." (PMID 35911648, 2022). "As an essential transcriptional inhibitor, ZBTB7A presents an abnormal expression in non-small cell lung cancer, breast cancer, and other cancers." (PMID 35012438, 2022). "Meanwhile ALPP, JUND, ZBTB7A in gastric cancer, prostate cancer, breast cancer 33-35 and other cancers promote the progress of cancer." (PMID 32626531, 2020). "ZBTB7A, though its proper function in the breast cancer pathway is unknown, acts as a tumor suppressor making it a novel target for combating breast cancer, while PATZ1 possesses the potential for being a suitable candidate for the suppression of cancer." (PMID 28607444, 2017). "In addition, ERα potentiates ZBTB7A expression via a positive loop in breast cancer." (PMID 38509416, 2024). "LRF (ZBTB7A) is an oncogenic transcription factor that is induced by TGF-β1 and is aberrantly expressed in breast cancer tissue." (PMID 30914750, 2019). "ZBTB7A ChIP-seq data is not available in breast cancer cell lines." (PMID 30404658, 2018).
prostate carcinoma (12 papers, 2014 to 2025). A carcinoma that arises from epithelial cells of the prostate gland. "Wang and colleagues identified that loss of the zinc finger and BTB domain-containing protein 7a (Zbtb7a) gene accelerates oncogenesis in PTEN loss-driven prostate cancers via a SRY box 9 (SOX9) dependent pathway for cellular senescence bypass and invasion." (PMID 25496077, 2014). "In prostate cancer, ZBTB7A is reported to induce cell proliferation in androgen insensitive prostate cancer cells (PC3) with increased ZBTB7A expression, while acting as a tumor suppressor in androgen sensitive prostate cancer cells (LNCaP)." (PMID 37065756, 2023). "On the other hand, ZBTB7A has been found to decrease cell progression and metastasis in melanoma and prostate cancer patients." (PMID 35501800, 2022). "Strikingly, LRF/ZBTB7A was also found to define the tumor microenvironment and the influx of tumor infiltrating immune cells in prostate cancer, and in particular the attraction of polymorphonuclear cells." (PMID 31823818, 2019). "ZBTB7A physically interacts with SOX9 and functionally antagonizes its transcriptional activity on key target genes; ZBTB7A inactivation determines Rib downregulation, bypass of PTEN loss-induced cellular senescence and invasive prostate cancer." (PMID 31366128, 2019). "However, the co-dependency with RET revealed the association of ZBTB7A in SCN HI cells, suggesting that co-dependency analysis with RET, a possible emerging NEPC target, can distinguish the roles of ZBTB7A in different prostate cancer subtypes." (PMID 37065756, 2023). "While some tumor suppressive mechanisms of ZBTB7A in specific prostate cancers have been reported, the oncogenic mechanism is unknown." (PMID 37065756, 2023). "Previous studies showed that ZBTB7A suppressed tumorigenesis in melanoma and prostate cancer." (PMID 35501800, 2022). "Both PTEN and Zbtb7a gene transcripts are targeted by the mir106b-25 cluster, providing further evidence of the importance of miRNA interaction with the PTEN pathway in prostate cancer development." (PMID 25496077, 2014).
leukemia (11 papers, 2006 to 2025). A malignant (clonal) hematologic disorder, involving hematopoietic stem cells and characterized by the presence of primitive or atypical myeloid or lymphoid cells in the bone marrow and the blood. "By contrast, mice with an inducible deletion of ZBTB7A (LRF, leukemia/lymphoma-related factor) exhibit a grossly normal thymic T-cell development, but an aberrantly increased number of extrathymic DP T cells in the bone marrow (BM) that is reversed by blocking NOTCH signaling." (PMID 34349770, 2021). "In summary, based on the results obtained in this study, we can claim that the regulators ZBTB7A and PU1 beside to BCLAF1 and NRSF play a significant role in cancer, and especially in leukemia." (PMID 33828122, 2021). "However, the highest degree nodes in this GRN are ZBTB7A and PU1 which play a significant role in cancer, especially in leukemia." (PMID 33828122, 2021). "These include mutations in genes known to cooperate with CBF-rearrangements [e.g. NRAS (n = 6), KRAS (n = 4), FLT3 (n = 2), KIT (n = 3), ZBTB7A (n = 2)] as well as in genes, which have not been described to be mutated in CBF leukemia so far (e.g. ZFHX4, NFE2, HERC1)." (PMID 31896782, 2020).
colorectal cancer (7 papers, 2019 to 2025). A primary or metastatic malignant neoplasm that affects the colon or rectum. "In contrast, LINC00473 was discovered to be transcriptionally silenced due to promoter hypermethylation in colorectal cancer and was suppressed in osteosarcoma cells by the direct binding of ZBTB7A (encoding Pokemon) to the LINC00473 promoter." (PMID 38512964, 2024). "For instance, considering that ZBTB7A can exert an oncogenic function in colorectal cancer patients, it can be taken as an underlying biomarker and therapeutic target for colorectal cancer." (PMID 35012438, 2022). "Similarly, ZBTB7A was reported to be overexpressed in colorectal cancer tissues and was linked to a poor prognosis." (PMID 35501800, 2022). "IN summary, our findings establish ZBTB7A as a promising molecular target for colorectal cancer therapy, acting through its regulation of both CD95 and JNK2 signaling pathways." (PMID 40953033, 2025). "ZBTB7A was increased in tumor tissues and promoted tumorigenesis in colorectal cancer, glioma and osteosarcoma." (PMID 35501800, 2022). "Despite zinc finger and BTB domain-containing 7A (ZBTB7A) documented importance in multiple tumors, the function and clinical value in Colorectal cancer (CRC) remain elusive." (PMID 33167891, 2020). "CD95 (also called Fas and APO-1) is a typical death receptor inducing cell apoptosis, but it has also been reported that CD95 could promote the growth of some tumors.Our screening has found that both CD95 and ZBTB7A are highly expressed in HCT116 colorectal cancer cells." (PMID 40953033, 2025). "Thus, we aim to further investigate the role of ZBTB7A in colorectal cancer." (PMID 40953033, 2025). "Our study demonstrates that ZBTB7A depletion reduces CD95 expression and suppresses colorectal cancer cell growth In HCT116 cells, ZBTB7A knockdown concurrently decreased JNK2 levels, suggesting its additional role in modulating cell survival/death through JNK2 signaling." (PMID 40953033, 2025).
gastric cancer (7 papers, 2016 to 2022). A primary or metastatic malignant neoplasm involving the stomach. "For example, miR-100 suppressed ZBTB7A expression in gastric cancer, whereas miR-663a downregulated ZBTB7A expression in osteosarcoma, and MiR-372 inhibited ZBTB7A expression in oral carcinoma." (PMID 35501800, 2022). "To delve into the function of lncRNA PURPL in the miR-137/ZBTB7A axis in the field of gastric cancer, we transfected miR-137 mimics (miR-137) or si-ZBTB7A into the AGS cell model with overexpression of PURPL." (PMID 35012438, 2022). "We screened eight DDR-related genes (ZBTB7A, POLQ, CHEK1, NPDC1, RAMP1, AXIN2, SFRP2, and APOD) to establish a risk model, which can predict the prognosis of gastric cancer patients and guide the clinical implementation of immunotherapy." (PMID 36578802, 2022). "In this study, attempts were made to explore lncRNA PURPL’s regulation on miR-137 and ZBTB7A molecules as well as its impact on the development of gastric cancer." (PMID 35012438, 2022). "Combination of C/EBPα and promoter in miR-100 could suppress tumor metastasis by targeting ZBTB7A in gastric cancer." (PMID 27050434, 2016).
colon cancer (6 papers, 2015 to 2026). "In addition, ZBTB7A overexpression has also been linked to tumorigenesis and metastasis in various cancer types, including breast, prostate, lung, ovarian and colon cancer." (PMID 35742860, 2022). "Despite a previous report in the context of colon cancer suggesting that ZBTB7A zinc finger mutations act in a dominant negative manner, we could not find any evidence for this effect in our models, even when the expression of the R402C mutant was slightly higher than the control." (PMID 32115572, 2020). "To further verify the function of ZBTB7A, we treated four colon cancer cell lines, HCT8, HCT116, HT-29, and SW620 with curcumin." (PMID 40953033, 2025). "Here we showed that ZBTB7A knockout inhibited the growth of colon cancer cells and reduced CD95 protein expression by decreasing CD95 mRNA transcription." (PMID 40953033, 2025). "In turn, ZBTB7A can directly repress the transcription of several genes implicated in glycolysis (SLC2A3, PFKP, and PKM) in an MYC-independent manner, and ZBTB7A knockdown in a colon cancer cell line resulted in increased glycolysis and proliferation." (PMID 32115572, 2020). "Moreover, they found that low ZBTB7A expression correlates with poor prognosis in colon cancer patients, suggesting that ZBTB7A plays a tumour suppressor function in these cancers." (PMID 26187947, 2015). "Interestingly, this study also found that in colon cancer xenografts, ZBTB7A represses the expression of genes in the glycolytic pathway, a metabolic pathway that is required for aggressive tumour growth, and that inhibition of this pathway reduces tumour growth." (PMID 26187947, 2015). "In this study, we illustrated that ZBTB7A positively regulates the expression of CD95 and the growth of colon cancer cells, providing a potential target for the treatment of colon cancer." (PMID 40953033, 2025). "To investigate the role of ZBTB7A in colon cancer cells, we firstly detected its expression in SW620, HT-29, HCT8, and HCT116 colon cancer cells." (PMID 40953033, 2025).
osteosarcoma (6 papers, 2018 to 2024). A usually aggressive malignant bone-forming mesenchymal neoplasm, predominantly affecting adolescents and young adults. "In osteosarcoma, ZBTB7A represses linc00473 transcription and expression and regulates the sensitivity of osteosarcoma cells to cisplatin chemotherapy." (PMID 37066523, 2023). "In osteosarcoma, ZBTB7A has been shown to increase chemoresistance and protect osteosarcoma cells from ER stress-induced apoptosis." (PMID 35501800, 2022). "In particular, miR-663a and ZBTB7A were found to protect osteosarcoma from endoplasmic reticulum stress-induced apoptosis, through the down-regulation of GAS5, while in a similar study the CtBP1-HDAC1/2-IRF1 transcriptional complex was also found to be down-regulated in osteosarcoma cells." (PMID 33076450, 2020).
acute myeloid leukemia (5 papers, 2016 to 2022). Acute myeloid leukemia (AML) is a group of neoplasms arising from precursor cells committed to the myeloid cell-line differentiation. "The ZBTB7A mutation may collaborate with the RUNX1-RUNX1T1 fusion gene in two ways and could be a new target to treat acute myeloid leukemia (AML)." (PMID 35629383, 2022).
glioma (5 papers, 2019 to 2025). A benign or malignant brain and spinal cord tumor that arises from glial cells (astrocytes, oligodendrocytes, ependymal cells). "Profiling of various tumor samples and normal brain (NB) tissues from the TCGA and the Genotype-Tissue Expression (GTEx) projects in GEPIA confirmed that ZBTB7A expression was lower in GBM and lower-grade glioma tissues than in NB tissues." (PMID 36596853, 2023).